Y_RNA (Y RNA )
Gene: Miscellaneous RNA gene on chromosome 4 (166,312,935 to 166,313,034, reverse strand). Ensembl gene ENSG00000206711.
Homologues: Orthologues: chimpanzee Y_RNA (99% identical), macaque Y_RNA (94% identical). Paralogues in human: Y_RNA (89% identical), Y_RNA (88% identical), RNY3 (87% identical), Y_RNA (87% identical), Y_RNA (86% identical), Y_RNA (85% identical), RNY3P1 (84% identical), Y_RNA (84% identical), RNY3P14 (83% identical), RNY3P16 (83% identical), Y_RNA (83% identical), RNY3P13 (82% identical), and 95 more.